MPO (myeloperoxidase)
Diseases named in the same sentence as MPO in open-access papers (continued):
Sharing a sentence is not in itself a finding about the gene and the disease.
Stroke (continued). "However, the impact of extracellular MPO and NE on post-stroke immune responses and patient outcomes still needs to be determined." (PMID 28732504, 2017). "The increased amounts of MPO and NE post-stroke might be caused by increased release due to phagocyte cell death including NETosis by degradation of NET and post-stroke granulocytosis." (PMID 28732504, 2017). "Although the intracellular amount of MPO was reduced, which may result in impaired intracellular killing of engulfed bacteria, the extracellular levels of MPO and NE were elevated in stroke patients." (PMID 28732504, 2017). "MPO has been suggested as a biomarker for diagnosis and prognosis of stroke." (PMID 27220420, 2016). "In stroke, tissue MPO levels are routinely used to assess neutrophil infiltration." (PMID 27220420, 2016). "However, recent studies suggest that MPO plays a detrimental role in stroke via its ability to generate highly reactive oxidants and toxic free radicals." (PMID 27220420, 2016). "Moreover, increased MPO activity in ischemic stroke models correlates with the degree of neutrophil infiltration, oxidative damage, and inflammation, suggesting its pivotal role in stroke pathology." (PMID 40076473, 2025). "This suggests that MPO could serve as a supplementary biomarker for stroke severity assessment." (PMID 41281270, 2025). "Interestingly, we found decreased percentage of MPO+ cells and lower MPO protein levels in aged on day 3, suggesting that most Iba1+ cells in aged mice have degranulated and secreted MPO in response to stroke." (PMID 39325942, 2024). "As MPO activity increases oxidative stress and elevated oxidative stress is associated with aging, aging-related changes and elevated abnormal MPO activity, as we found in the aged mice after stroke, may form a vicious cycle that worsens each other and leads to higher mortality." (PMID 39325942, 2024). "Interestingly, reduced recruitment of neutrophils was observed in the neutrophil-like cell-membrane-coated mesoporous Prussian blue nanozyme (MPBzyme@NCM) treated tMCAO/stroke mice at day 5 after stroke, as indicated by Western blotting analyses of myeloperoxidase, a marker for neutrophils." (PMID 38549161, 2024). "Furthermore, this reduction in MPO activity translated into significant improvement in neurobehavioral performance and mortality rate within the aged group approaching the level seen in young adult stroke mice." (PMID 39325942, 2024). "Thus, MPO inhibition might offer a promising therapeutic target for stroke therapy via attenuating oxidative damage and neuroinflammation in ischemic stroke." (PMID 36552554, 2022). "CitH3+ NETs retrieved in thrombi.CitH3+ MPO+NE+ NETs in brain tissue.NETs as scaffold responsible for platelet adhesion and thrombus resistance to t-PA.NETs content in the cerebral thrombus differs according to stroke etiology.Thrombus NETs content correlates with NETs plasma level at stroke onset." (PMID 35844591, 2022). "High MPO serum levels predict risk for early cardiac events in patients with the acute coronary syndrome, as well as major adverse cardiovascular events (death, nonfatal myocardial infarction and stroke)." (PMID 35175161, 2022). "Thus, MPO inhibition may represent a therapeutic perspective in post-stroke patients, improving neuronal functionality." (PMID 34821692, 2021). "Matrix metalloproteinase-9 and myeloperoxidase which considered as mediators of the neutrophil effects, and other potential mediators such as elastase and leukotriene B4 derived from neutrophils need to be evaluated in following research to verify the correlation with circCDC14A after stroke." (PMID 34876161, 2021). "Apart from MMP, other factors released after stroke, including reactive oxygen species(ROS), cathepsin G, proteases, myeloperoxidase, elastase, chemokines and cytokines, may also destroy neurovascular units, ultimately increasing the permeability of the BBB and the risk for HT." (PMID 32028265, 2020).
Stroke (continued). "Interestingly, tMCAO had a significantly higher MPO level in the ischemic cortex than the pMCAO model after stroke onset, indicating that reperfusion could aggravate the activation of MPO for neuroinflammation." (PMID 32508671, 2020). "Furthermore, the MPO-mediated inflammation affects post-stroke neurogenesis." (PMID 32508671, 2020). "Importantly, MPO inhibition may represent a promising therapeutic target for stroke therapy, particularly even days after the stroke has occurred." (PMID 32508671, 2020). "Therefore MPO imaging could potentially be used in a clinical setting to validate therapeutic effects of anti-inflammatory treatment in stroke patients." (PMID 29335483, 2018). "Therefore, SCAD patients with a high MPO concentration > 300 ng/ml and a high concentration of inflammatory markers and reduced concentration of apoAI and HDL-C in which LpPLA2 was increased are at the risk of ACS and stroke." (PMID 29618370, 2018). "Intracellular reduction of MPO might be responsible for reduced NETosis in stroke patients." (PMID 28732504, 2017). "Thus, the reduction of intracellular MPO could contribute to the impaired oxidative burst as well as the reduced NET area in stroke patients." (PMID 28732504, 2017). "In addition to neutrophil-derived MMPs, other factors released from neutrophils after stroke, including ROS, myeloperoxidase, elastase, cathepsin G, proteinase 3, cytokines, and chemokines, can also disrupt the neurovascular unit and ultimately result in increased BBB permeability and HT." (PMID 27561990, 2016). "The MPO-DNA, an accurate marker of NET formation, peaks around 24 h post-stroke, representing an optimal therapeutic window." (PMID 40290435, 2025). "The myeloid enzyme myeloperoxidase (MPO) generates oxidative stress and contributes to damage after stroke." (PMID 39325942, 2024). "The levels of MPO-DNA, PAD4, C1q, IL-1β, IL-6, IL-8 and HMGB1 change significantly over time during the acute phase of stroke (all P < 0.05)." (PMID 39737165, 2024). "The serum MPO-DNA, PAD4, C1q, IL-1β, IL-6 and IL-8 reach their peak at 24 hours after stroke onset and show a decreasing trend during acute phase." (PMID 39737165, 2024). "MPO inhibition in aged mice decreased MAFA signal and Iba1+ cells and improved neurobehavioral outcomes to near young adult stroke mice levels and improved mortality rate." (PMID 39325942, 2024). "Notably, the administration of ABAH, a specific and irreversible inhibitor of MPO, exhibited remarkable outcomes in mitigating the inflammatory response, reducing MPO activity, enhancing neurological outcomes, and improving the mortality rate in the aged group after stroke." (PMID 39325942, 2024). "On day 10 after the stroke, while MAFA signal markedly decreased from that of day 3, higher MAFA signal and MPO protein were still detected in the aged brains compared to those of the young adult." (PMID 39325942, 2024). "The production of myeloperoxidase from these cells exacerbates the damage to the BBB and contributes to fuel neuroinflammation, even after stroke is resolved." (PMID 36901834, 2023). "According to previous studies, MPO is an important regulatory molecule in the development of ICH, which can participate in the development and prognosis of stroke in various ways." (PMID 36570834, 2022). "Studies have shown that the classic MPO inhibitor, 4-aminobenzoic acid hydrazide (ABAH), can inhibit MPO activity, increase the proliferation of stroke neurons, and improve neurogenesis." (PMID 36570834, 2022). "We perform linear logistic regression of stroke and coronary artery disease (CAD) using MPO genetic scores and clinical predictors." (PMID 35504531, 2022). "Immunoblotting and densitometric analysis show that MPO protein levels were dramatically induced by stroke in the ipsilateral cortex of COX-2+/+ mice, and very low levels of MPO were detected in the COX-2−/− mice compared to the wild-type animals." (PMID 32973660, 2020).
Stroke (continued). "Given the reality that most stroke patients cannot make the golden therapeutic window for thrombolysis, further investigations in this aspect may create a novel therapeutic window for improving the outcome of ischemic stroke by reducing the MPO-mediated inflammation and oxidative injury practically." (PMID 32508671, 2020). "Additionally, the inhibition of MPO in EAE and stroke mice models decreased BBB permeability and diminished disease severity." (PMID 40362673, 2025). "both MPO and CD19 expression in the meningeal tissue exhibited a consistent upward trend among patients, suggesting a potential correlation between immune cell infiltration and stroke severity." (PMID 40313936, 2025). "Notably, on the 3rd day post-stroke, a marked decrease was found in both MAFA and Iba1+ signals in the aged group after treatment with ABAH, revealing that inhibition of MPO activity resulted in a reduced recruitment of Iba1+ cells to the infarcted area." (PMID 39325942, 2024). "For detail, MPO-DNA, PAD4, C1q, IL-1β, IL-6 and IL-8 reached their peak at 24 hours after stroke onset and show a decreasing trend throughout the acute phase of stroke, while HMGB1 peaked at 48 hours after stroke onset." (PMID 39737165, 2024). "Therefore, investigation the prognostic value of markers in the NETs/AIM2 inflammasome axis, such as MPO-DNA, PAD4, HMGB1, C1q, AIM2, ASC, Caspase-1, IL-1β, IL-6 and IL-8, in LAA stroke patients is a meaningful endeavor." (PMID 39737165, 2024). "A representative histologic specimen without further vascular events had a reduced number of MPO-positive cells, but more intense PD-L1 expression compared with those of a patient who suffered from stroke after femoral endarterectomy." (PMID 38172197, 2024). "In population B, MPO and Anti Apo A1 were significantly higher in patients who had suffered a stroke compared to those without prior stroke." (PMID 35042473, 2022). "As in stroke patients, we observed 3 types of neutrophils (Ly6G and MPO double positive): (a) H3cit-negative, non-NETting neutrophils; (b) extracellular NETs; and (c) neutrophils in the early stages of NET formation." (PMID 35358095, 2022). "Together with the low MPO activity, this may be a hint that NET-formation is taking place in the VITT patient even after the stroke event, but with less frequency in the control group." (PMID 35619694, 2022). "In our study, we found the expression of MPO increased significantly post stroke as compared to the sham group (p < 0.01), while knockout of FXR reduced the level of MPO in the peri-infarct area of brain striatum (p < 0.05) in comparison with the vehicle group." (PMID 32450881, 2020). "Immunohistochemistry revealed that there were similar numbers of CD45+ leukocytes, neutrophils (MPO+), T cells (CD3+), astrocytes (GFAP+) and microglia-macrophages in the ischemic hemisphere of WT compared with IL-37tg mice after stroke." (PMID 31061403, 2019). "None of the intra- und extracellular MPO and NE parameters correlated with stroke severity or neutrophil numbers." (PMID 28732504, 2017). "It was previously reported that r-tPA leads to degranulation of neutrophils, thus increasing NE and MPO in serum, and that r-tPA reduces stroke lesion size or outcomes independent of successful recanalization." (PMID 28732504, 2017). "Reduced intracellular MPO could explain the impaired oxidative burst and reduced NET area in stroke patients." (PMID 28732504, 2017). "In stroke patients, MPO levels at 6 h where not different compared to controls (57.99 vs 45.95 ng/ml, respectively, p > 0.05)." (PMID 26792363, 2016). "We next assessed MPO activity in both aged and young adult naïve brains without stroke using MAFA." (PMID 39325942, 2024). "MPO is a common inflammatory marker, and elevated MPO levels are observed in many pathological conditions, including inflammatory bowel disease (IBD), cardiovascular disease, obesity, liver disease, arthritis, multiple sclerosis, Alzheimer’s disease, stroke and cancer." (PMID 36293108, 2022).
Stroke (continued). "Myeloperoxidase (MPO) staining identified hypochlorous acid-producing neutrophils in the brain, found both within claudin 5-stained vasculature and in the parenchyma, were significantly increased after stroke in old subjects (> 71 years old) compared to young (≤ 71 years old) stroke subjects." (PMID 29752550, 2018). "On the basis of these findings, we conclude that MPO-mediated oxidative stress plays an important role in the mechanisms by which stroke induces oxidative injury to the brain and accordingly KYC should be a highly effective therapeutic agent for treating patients with stroke." (PMID 27220420, 2016). "In addition, specificity of MPO-Gd in vivo was confirmed by imaging MPO-knockout stroke mice, in which no specific MPO enhancement was detected." (PMID 25525560, 2014). "A study using endothelin-1-induced cerebral ischemia in rats (ET-1 model) showed that infiltrated neutrophils are phagocytized by macrophages in the first 3 days after stroke onset, but MPO activity keeps increasing, suggesting that MPO may not be the best measurement for neutrophil accumulation." (PMID 31849964, 2019).
coronary artery disease (117 papers, 2008 to 2025). "Elevated MPO levels have been associated with increased risks of cardiovascular mortality and severity of coronary artery disease." (PMID 39134772, 2025). "Increased plasma levels of MPO are associated with an increased risk of coronary artery disease, and MPO-DNA complexes are positively correlated with severe adverse cardiovascular events." (PMID 41511355, 2025). "Myeloperoxidase (MPO), an important inflammatory biomarker associated with various diseases, such as ischemic heart disease and acute coronary syndrome, has gained attention as a potential biomarker for myocardial infarction and cognitive decline." (PMID 39204198, 2024). "In studies, MPO was strongly associated with an increased risk of coronary artery disease and acute HF, being a promising biomarker of cancer therapy-related cardiotoxicity in BC patients treated with anthracyclines and trastuzumab." (PMID 38066798, 2023). "Polymorphisms in the myeloperoxidase gene have been linked to premature ischemic heart disease, ischemic heart disease intensity,and heart failure mortality." (PMID 35815198, 2022). "Elevated levels of MPO are also associated with pathology such as coronary artery disease and endemic arsenic poisoning." (PMID 35933350, 2022). "Subjects carrying the G-463A MPO polymorphism have higher levels of total and low-density lipoprotein-associated cholesterol, and elevated risk for coronary artery disease, MPO-ANCA vasculitis, lung, and pancreas cancer." (PMID 36421487, 2022). "Further studies should address the effects of statin in individuals with G-463A MPO polymorphism, a known risk factor for coronary artery disease." (PMID 36421487, 2022). "Patients with coronary artery disease and peripheral artery disease have increased MPO blood levels, which are associated with poor prognosis and cardiovascular mortality." (PMID 34639156, 2021). "Myeloperoxidase (MPO) (produced and secreted by leukocytes) has atherogenic and pro-oxidant effects on cardiac tissue leading to its association with increased risk of coronary artery disease and acute HF." (PMID 32642841, 2020). "Of specific relevance is that elevated MPO levels predict future risk of coronary artery disease in healthy individuals." (PMID 33081376, 2020). "Previous investigations have implicated NETs in coronary artery disease, and the present report correlates systemic inflammation and IL-1β with MPO-DNA complexes, currently considered an established assay for NETosis in vivo." (PMID 31779200, 2019). "Myeloperoxidase gained special importance in 2001, due to its association with coronary artery diseases (CAD)." (PMID 29669993, 2018). "MPO-mediated inflammation has been implicated in multiple diseases including coronary artery disease and glomerular and tubulointerstitial kidney diseases." (PMID 28135312, 2017). "Elevated circulating MPO levels have been found to be associated with the presence of coronary artery disease (CAD)." (PMID 28770019, 2017). "Plasma MPO levels have been positively associated with coronary artery disease (CAD) and risk of a subsequent cardiac event." (PMID 24594096, 2014). "Myeloperoxidase (MPO), a marker of inflammation in coronary artery disease, is thought to be implicated in the inflammatory process of CVS." (PMID 24058736, 2013). "Subjects with total or subtotal MPO deficiency, a defect with a frequency of about 1 in 2000-4000 Caucasians, have lower incidence of coronary artery disease (CAD)." (PMID 22014237, 2011). "Some biomarkers such as myeloperoxidase and high-sensitivity C-reactive protein in an apparently healthy population predicts risk of coronary disease and allows clinicians to initiate early preventative treatment." (PMID 20529285, 2010). "However, lipoprotein-associated phospholipase A2 (Lp-PLA2) and myeloperoxidase (MPO) are more relevant to coronary disease, as they target plaque-specific processes, such as the hydrolysis of oxidized phospholipids and neutrophil activation." (PMID 41511355, 2025).